SEC24B (SEC24 homolog B, COPII component)
Description:
Component of the coat protein complex II (COPII) which promotes the formation of transport vesicles from the endoplasmic reticulum (ER). The coat has two main functions, the physical deformation of the endoplasmic reticulum membrane into vesicles and the selection of cargo molecules for their transport to the Golgi complex. Plays a central role in cargo selection within the COPII complex and together with SEC24A may have a different specificity compared to SEC24C and SEC24D. May package preferentially cargos with cytoplasmic DxE or LxxLE motifs and may also recognize conformational epitopes.
Synonyms: SEC24
Tractability: Antibody: UniProt places it where antibodies can reach, with high confidence. PROTAC: ubiquitination databases record sites on it; its protein half-life has been measured.
Gene: Protein-coding gene on chromosome 4 (109,433,602 to 109,540,896, forward strand). Ensembl gene ENSG00000138802.
Subcellular location: Cytoplasmic vesicle, COPII-coated vesicle membrane; Endoplasmic reticulum membrane; Cytoplasm, cytosol
Subcellular location (Human Protein Atlas): Nucleoplasm; Vesicles
Pathways (Reactome):
Immune System: Antigen Presentation: Folding, assembly and peptide loading of class I MHC; MHC class II antigen presentation
Vesicle-mediated transport: COPII-mediated vesicle transport; Cargo concentration in the ER
Disease: SARS-CoV-2 activates/modulates innate and adaptive immune responses
Metabolism: Regulation of cholesterol biosynthesis by SREBP (SREBF)
Gene Ontology:
Molecular function: protein binding; zinc ion binding; SNARE binding
Biological process: COPII-coated vesicle cargo loading; endoplasmic reticulum to Golgi vesicle-mediated transport; positive regulation of ER to Golgi vesicle-mediated transport; intracellular protein transport
Cellular component: COPII vesicle coat; cytosol; endoplasmic reticulum membrane; endoplasmic reticulum; ER to Golgi transport vesicle membrane
Genetic constraint (gnomAD): Loss-of-function variants: 24 observed, 76.34 expected, observed/expected ratio (o/e) 0.31, 90% interval 0.23 to 0.44. The upper end of that interval is the gene's LOEUF score, 0.44, which puts it in group 1 of 6, group 1 being the genes least tolerant of losing a copy. Missense variants: 1,016 observed, 1,075.7 expected, observed/expected ratio (o/e) 0.94, 90% interval 0.9 to 1. Synonymous variants: 434 observed, 421.22 expected, observed/expected ratio (o/e) 1.03, 90% interval 0.95 to 1.12.
Homologues: Orthologues: chimpanzee SEC24B (99% identical), macaque SEC24B (97% identical), dog SEC24B (93% identical), pig SEC24B (92% identical), rabbit SEC24B (89% identical), rat Sec24b (83% identical), mouse Sec24b (83% identical), guinea pig SEC24B (80% identical), tropical clawed frog sec24b (59% identical), zebrafish sec24b (57% identical), Drosophila melanogaster Sec24AB (38% identical), Caenorhabditis elegans sec-24.2 (31% identical). Paralogues in human: SEC24A (51% identical), SEC24D (22% identical).
Diseases named in the same sentence as SEC24B in open-access papers:
SEC24B is named in the same sentence as 22 diseases in open-access papers, as found by Europe PMC text mining. Sharing a sentence is not in itself a finding about the gene and the disease. The quoted sentences say what the papers report.
craniorachischisis (5 papers, 2010 to 2018). Craniorachischisis is the most severe form of neural tube defect in which both the brain and spinal cord remain open to varying degrees. "Two separate mutations in Sec24b also disrupt Vangl2 trafficking resulting in similar craniorachischisis phenotypes." (PMID 22363783, 2012). "Craniorachischisis occurs following mutation of Sec24b, a protein recently shown to affect membrane localisation of Vangl2." (PMID 20704721, 2010). "Most recently, mutation of Sec24b has been shown to cause craniorachischisis, and Sec24b affects PCP through regulation of Vangl2 protein trafficking." (PMID 20704721, 2010). "Similarly, there is an essential requirement for Sec24B in the trafficking of the planar cell polarity protein Vangl2; mutations in Sec24B in mice cause craniorachischisis and related mutations in humans result in neural tube defects." (PMID 29916038, 2018). "Consistent with this hypothesis, mutations in sec24b, which encodes an ER transport protein that is required for Vangl2 movement to the plasma membrane, result in craniorachischisis similar to Lp." (PMID 22363783, 2012). "In contrast, in craniorachischisis, Sec24b is affected but also with rather limited effects (although severe)." (PMID 21235735, 2011). "In some examples, mutants are homozygous at only one PCP gene (e.g., Vangl2, Celsr1, Scrib or Sec24b) and all embryos have craniorachischisis; heterozygotes do not." (PMID 30134561, 2018).
acute lymphoblastic leukemia (1 paper, 2018). Leukemia with an acute onset, characterized by the presence of lymphoblasts in the bone marrow and the peripheral blood. "miR-576-3p is an intronic miRNA embedded within SEC24B (SEC24 homolog B, COPII coat complex component gene) and is suppressed in bladder cancer, T-cell precursor acute lymphoblastic leukemia, and sera of non-melanoma skin cancer patients (BCC and SCC, UV light related)." (PMID 30114287, 2018).
Alzheimer disease (1 paper, 2023). A progressive, neurodegenerative disease characterized by loss of function and death of nerve cells in several areas of the brain leading to loss of cognitive function such as memory and language. "Although SEC24B has not been identified before as a regulator of ferroptosis, it is significantly upregulated in multiple neurodegenerative diseases, including ALS, multiple system atrophy, frontotemporal lobar degeneration and Alzheimer’s disease." (PMID 36536241, 2023).
spina bifida (1 paper, 2024). A congenital neural tube defect in which vertebrae are not fully formed. "Upon follow-up, spina bifida was identified in this patient, implicating the hypoplasia of the spine and the neural tube that are potentially associated with the SEC24B variant." (PMID 38321032, 2024).
steatosis (1 paper, 2021). Increased lipid within the cytoplasm of cells. "However, the results obtained for other genes negatively associated with serum ferritin in this cohort with steatosis seemed counterintuitive (GYS2, SEC24B, SOCS2)." (PMID 33962692, 2021).
cancer (4 papers, 2018 to 2024). A tumor composed of atypical neoplastic, often pleomorphic cells that invade other tissues. "To analyze the potential mechanisms underlying the cancer-promoting effect of circSEC24B, we explored the impacts of circSEC24B on the expression of its parent gene SEC24B." (PMID 39333496, 2024). "In addition, we identified three heterozygous candidate missense variants in known cancer susceptibility genes (BMPR1A,BRIP1, and SRC), three truncating variants in possibly novel cancer genes (CLSPN,SEC24B, SSH2) and four candidate missense variants in ACACA, NR2C2, INPP4A, and DIDO1." (PMID 30809968, 2019). "To date, no studies have implicated RBM27, SEC24B, or SSH2 in CRC or cancer development." (PMID 30809968, 2019).
infection (4 papers, 2023 to 2025). The state of being infected such as from the introduction of a foreign agent such as serum, vaccine, antigenic substance or organism. "We could only consistently isolate Sec24b in association with L2-HA in the cells that had unimpeded infection." (PMID 40431628, 2025). "Our results showed that STING interacted with HOIP and Sec24b at the early stage of HSV‐1 infection and then bound to OTULIN at the late stage of the infection." (PMID 40536345, 2025). "At the early stage of the infection, LUBAC promotes STING linear ubiquitination to drive its trafficking from the endoplasmic reticulum (ER) to the Golgi apparatus through binding to the Sec24b subunit of the coat protein complex II (COPII) complex." (PMID 40536345, 2025). "Vero-E6 cells were transfected with Sec23A or Sec24B small interfering RNA (siRNA), followed by infection with PEDV with or without TSA treatment." (PMID 37766280, 2023).
SEC24B also shares sentences with these, for which no sentence is quoted: tumor (2 papers); bladder cancer (1); bladder urothelial carcinoma (1); chylomicron retention disease (1); congenital dyserythropoietic anemia type 2 (1); craniolenticulosutural dysplasia (1); frontotemporal lobar degeneration (1); hepatoma (1); immune disorders (1); leukemia (1); lung disease (1); melanoma (1); multiple system atrophy (1); neural tube defect (1); neurodegenerative disease (1).